U7 (U7 small nuclear RNA )
Synonyms: LOC124904756
Gene: Small nuclear RNA gene on chromosome 1 (176,217,541 to 176,217,602, forward strand). Ensembl gene ENSG00000273629.
Homologues: Orthologues: chimpanzee U7 (100% identical), guinea pig U7 (68% identical), guinea pig U7 (66% identical), guinea pig U7 (65% identical), guinea pig U7 (61% identical), rat LOC120101218 (61% identical), rat LOC120096373 (60% identical), rat LOC120100216 (60% identical), rat LOC120101993 (60% identical), tropical clawed frog U7 (60% identical), rat LOC120093934 (58% identical), rat LOC120096771 (58% identical), and 15 more. Paralogues in human: RNU7-37P (71% identical), RNU7-130P (69% identical), RNU7-171P (69% identical), RNU7-24P (69% identical), RNU7-80P (69% identical), RNU7-136P (68% identical), RNU7-18P (68% identical), RNU7-28P (68% identical), RNU7-40P (68% identical), RNU7-69P (68% identical), RNU7-70P (68% identical), RNU7-97P (68% identical), and 141 more.